COX5A (cytochrome c oxidase subunit 5A)
Diseases named in the same sentence as COX5A in open-access papers (continued):
Sharing a sentence is not in itself a finding about the gene and the disease.
tumor (15 papers, 2012 to 2025). "We next investigated whether high COX5A expression was linked to key clinicopathological parameters by comparing tumours with high versus low COX5A expression levels." (PMID 41184196, 2025). "In this study, we investigate the potential of COX5A as a key regulator of metabolic reprogramming in GC cells and its contribution to tumour progression." (PMID 41184196, 2025). "Conversely, COX5A‐OE tumours from AGS cells showed marked increases in volume and weight compared to Vector controls." (PMID 41184196, 2025). "We first confirmed that COX5A expression was significantly higher in tumour tissues compared to paired adjacent normal tissues (p < 0.001)." (PMID 41184196, 2025). "The positive expression rate of COX5A in tumour tissues was significantly higher (74.74%, 71/95) compared to adjacent normal tissues (12.63%, 12/95), with this difference being statistically significant." (PMID 41184196, 2025). "Our findings extend current understanding by demonstrating that COX5A‐driven mitochondrial bioenergetics not only fulfil the heightened energy demands of proliferating tumour cells but also create a permissive metabolic environment for GC progression." (PMID 41184196, 2025). "Future studies should address COX5A isoform specificity, evaluate its role in therapeutic resistance, and explore its interaction with tumour microenvironmental factors." (PMID 41184196, 2025). "Quantitative IHC revealed reduced p‐AKT (Ser473) in shCOX5A tumours and enhanced activation in COX5A‐OE tumours, directly linking COX5A to PI3K/AKT pathway activation." (PMID 41184196, 2025). "Quantitative analysis demonstrated significantly elevated COX5A mRNA expression in tumour tissues relative to adjacent normal tissues." (PMID 41184196, 2025). "In tumor cells, Bcl-2 interacts with COX5a, which results in the alteration of mitochondrial respiration under oxidative stress." (PMID 34685389, 2021). "Given that high ROS potentiates JNK-dependent MMP1 induction, most of the RNAi lines tested (ATPsynβ-RNAi, sdhC-RNAi and cox5A-RNAi) need to be accompanied by simultaneous overexpression of ROS scavengers in order to reduce Hipk tumor growth." (PMID 33199523, 2020). "Notably, COX5A expression was highest in Stage I tumours and subsequently decreased in Stages II and III, suggesting a potential role in early tumourigenesis." (PMID 41184196, 2025). "COX5A was upregulated in tumours and correlated with poor survival." (PMID 41184196, 2025). "Additionally, a significant difference in COX5A expression was observed between tumour tissues and normal tissues within the same samples (p < 0.001)." (PMID 41184196, 2025). "In vivo, COX5A silencing suppressed xenograft tumour growth." (PMID 41184196, 2025). "COX5A expression was significantly elevated in tumour tissues compared to normal tissues." (PMID 41184196, 2025). "The gene expression of citrate synthase (CS), related to oxidative metabolism, was similar between tumour-bearing groups (LW = W), and Cox5a gene expression, which is important to maintaining the normal mitochondrial function, was higher in LW in comparison to W group." (PMID 34943780, 2021). "Given this, COX5A may emerge as a potential biomarker and therapeutic target for GC, as its upregulation could drive metabolic adaptations that enhance cancer cell survival and tumour progression." (PMID 41184196, 2025). "We found that leucine supplementation led to increased Cox5a gene expression, even though oxygen consumption did not change between both tumour-bearing groups." (PMID 34943780, 2021). "In a landmark study, ClpP was identified among a subset of deregulated mitochondrial enzymes, alongside cytochrome c oxidase subunit 5A (COX5A) and enoyl-CoA hydratase 1 (ECH1), suggesting impairments in redox homeostasis, mitochondrial protein quality control, and metabolic rewiring in tumor cells." (PMID 41155556, 2025).
tumor (continued). "We hypothesize that COX5A facilitates GC progression by enhancing mitochondrial ATP synthesis through OXPHOS, thus supporting the bioenergetic demands of rapidly proliferating tumour cells." (PMID 41184196, 2025). "Knockdown of pdsw, but not ATPsynβ, sdhC or cox5A, abrogated Hipk-induced tumor-like growth." (PMID 33199523, 2020). "The largest number of changes in gene expression (n = 8) between tumour and non-malignant groups were identified in metabolic genes (PFKL, ATP5A1, UQCRFS1, CPT2, COX5A, ACLY, GPD2, and G6PD)." (PMID 36142793, 2022).
cancer (7 papers, 2016 to 2025). A tumor composed of atypical neoplastic, often pleomorphic cells that invade other tissues. "Given that metabolic reprogramming is a hallmark of cancer progression and therapy resistance, it is plausible that COX5A‐driven mitochondrial energetics contributes to acquired resistance in GC." (PMID 41184196, 2025). "Such metabolic reprogramming mirrors the adaptive strategies employed by cancer cells to thrive in nutrient‐scarce microenvironments, with COX5A emerging as a gatekeeper of mitochondrial efficiency in malignant transformation." (PMID 41184196, 2025). "Notably, the enhanced mitochondrial ATP production mediated by COX5A aligns with broader observations linking mitochondrial hyperactivity to cancer cell survival, proliferation, and resistance to apoptosis—a hallmark of aggressive malignancies." (PMID 41184196, 2025). "Recent studies suggest that alterations in COX5A expression and activity may contribute to the dysregulated energy metabolism observed in cancer cells, although its specific role in GC progression remains unclear." (PMID 41184196, 2025). "Additionally, fatty acid metabolism‐related genes, including Acaa2, Mdh2 and Ech1, as well as oxidative phosphorylation‐related genes, such as Sdhc, Cox5a and Mdh1, also upregulated in KAR cancer cells." (PMID 40621620, 2025). "The genes encoding the metabolic enzymes for oxidation phosphorylation such as Atp5l, Cox4i1, Cox5a, Cox7a2, Ndufc2, Ndufs4, Sdhd, Uqcrq28 were significantly downregulated in 20(S)/(R)-Rh2E2-treated LLC-1 cancer cells, but not in normal cells." (PMID 32796841, 2020).
infection (3 papers, 2020 to 2025). The state of being infected such as from the introduction of a foreign agent such as serum, vaccine, antigenic substance or organism. "In response to infection, in male mice, the TACC2, BUB1B, ATP5MC3, and MYO1E, and in female mice, the CAP1, MRPL2, COX5A, KLHL21, PDIA6, TSPO, and USP14 had direct interaction with TP-53." (PMID 35844510, 2022).
central nervous system diseases (2 papers, 2020). "Multiple studies reported that the expression of COX5A decreased in a variety of central nervous system diseases, which in turn caused an imbalance in neuronal energy regulation." (PMID 32349668, 2020). "These indicated that increasing COX5A expression may exert neuroprotective effect on the central nervous system diseases." (PMID 32349668, 2020).
neurodegenerative disease (2 papers, 2015 to 2025). A disorder of the central nervous system characterized by gradual and progressive loss of neural tissue and neurologic function. "In contrast, in PF tissue, genes like ATP5F1A, ATP5PO, SDHB, NDUFS8, SDHA, and COX5A play roles within the neurodegenerative disease pathway, and PF tissue has a positive impact on the process related to degenerative diseases." (PMID 40136641, 2025). "IF regulates lipid metabolism primarily via genes including FABP4, WNT10B, PCK1, PLIN1, LEPR, and ADIPOQ, providing energy for cold adaptation, whereas PF positively influences in vivo degenerative diseases mainly through genes such as ATP5F1A, ATP5PO, SDHB, NDUFS8, SDHA, and COX5A." (PMID 40136641, 2025).
heart disease (1 paper, 2021). "However, interestingly, there have been no reports of the functional correlation between Cox5a and hypoxia-induced heart disease." (PMID 34518647, 2021).
neurological diseases (1 paper, 2024). "Additionally, while no studies directly related to ALS were discovered, other studies related to other neurological diseases were found in the cases of the EEF1A1, COX5A and RPL12 and RPL15 genes." (PMID 38540795, 2024).
COX5A also shares sentences with these, for which no sentence is quoted: Parkinson disease (2 papers); adenocarcinoma (1); aging (1); blood cancer (1); cardiac hypertrophy (1); cardiovascular diseases (1); endometriosis (1); heart failure (1); hepatoma (1); Huntington disease (1); Hyperglycemia (1); Hypertension (1); lung adenocarcinoma (1); meningioma (1); Non-alcoholic fatty liver disease (1); non-small cell lung carcinoma (1); stomach adenocarcinoma (1); Stroke (1); type 2 diabetes (1).